DOT1L (DOT1 like histone lysine methyltransferase)
Diseases named in the same sentence as DOT1L in open-access papers (continued):
Sharing a sentence is not in itself a finding about the gene and the disease.
acute leukemia (14 papers, 2014 to 2025). A clonal (malignant) hematopoietic disorder with an acute onset, affecting the bone marrow and the peripheral blood. "Previous studies showed synergistic effects by combining the predecessor of revumenib, SNDX-50469 (VTP50469), with a DOT1L inhibitor in both KMT2A-rearranged and NPM1-mutated acute leukemia." (PMID 38892207, 2024). "Pinometostat represents a DOT1L inhibitor that has shown therapeutic potential for cases of acute leukemias involving mixed lineage leukemia (MLL) gene rearrangements." (PMID 38997742, 2024). "At this point, DOT1L has been found to be an important drug target for the therapy of acute leukemia with MLL gene translocations, and several kinds of DOT1L inhibitors were discovered in the past decade." (PMID 34425876, 2021). "If DOT1L can become an attractive target for the treatment of acute leukemia, it will be of great benefit to the medical field." (PMID 34149432, 2021). "The overexpression of HOXA9 and MEIS1 genes induced by the aberrant H3K79 methylation by DOT1L has been found in patients diagnosed with acute leukemias." (PMID 34500733, 2021). "Although the majority of studies dedicated to mammalian DOT1-like (DOT1L) are focused on its oncogenic role in acute leukemias, it is becoming clear that DOT1L has a profound impact on development." (PMID 32781660, 2020). "EPZ-5676, a small-molecule inhibitor of DOT1L, is currently under clinical investigation for acute leukemias harboring rearrangements of the MLL gene." (PMID 29665865, 2018). "Pinometostat (EPZ-5676), a DOT1L inhibitor, was tested in children with relapsed or refractory acute leukemias harboring MLL (KMT2A) gene rearrangement (MLL-r) as monotherapy in phase I clinical trial (NCT02141828), but no objective responses were observed in this cohort." (PMID 38997742, 2024). "Therefore, targeting DOT1L represents an attractive therapeutic option for patients diagnosed with KMT2A-rearranged acute leukemia, despite the first-in-class DOT1L inhibitor pinometostat showing dissatisfying results in adult patients." (PMID 37740239, 2023). "While next generation DOT1L inhibitors with improved pharmacokinetic profiles are in development, we reasoned that the mechanisms by which KMT2A-rearranged acute leukemia cells evade DOT1L inhibition may provide novel insights into the biology of these unique malignancies." (PMID 37740239, 2023). "Therefore, therapeutic degradation of DOT1L instead of solely inhibiting its catalytic activities might be beneficial in the treatment of KMT2A-rearranged acute leukemia." (PMID 37740239, 2023). "Histone methyltransferase DOT1L catalyzes mono-, di- and trimethylation of histone 3 at lysine residue 79 (H3K79) and hypermethylation of H3K79 has been linked to the development of acute leukemias characterized by the MLL (mixed-lineage leukemia) rearrangements (MLLr cells)." (PMID 34500733, 2021). "Accordingly, the development of the DOT1L inhibitor EPZ004777 and its successor EPZ5676 (pinometostat) were expected to become key to successful treatment of KMT2A-rearranged acute leukemias." (PMID 37740239, 2023). "In an in vivo clinical trial, the DOT1L inhibitor pinometostat can reduce H3K79 methylation and has moderate clinical activity in adult acute leukemia." (PMID 34149432, 2021). "If so, the identification of such DOT1L-independent oncogenic properties may well uncover important therapeutic targets and more effective treatment options for KMT2A-rearranged acute leukemias." (PMID 37740239, 2023). "DOT1L is the only known methyltransferase that catalyzes mono-, di- and tri-methylation of lysine 79 on histone H3 (H3K79me1/2/3) and has been identified as a critical component of oncogenic “Mixed Lineage Leukemia 1” (MLL1/KMT2A) complexes in KMT2A-rearranged and NPM1c mutant acute leukemia." (PMID 40781484, 2025).
acute leukemia (continued). "This may indicate that recently described biological functions of DOT1L that are independent of H3K79 methylation are also important for KMT2A-rearranged acute leukemia cells." (PMID 37740239, 2023).
acute myeloid leukemia (13 papers, 2014 to 2025). Acute myeloid leukemia (AML) is a group of neoplasms arising from precursor cells committed to the myeloid cell-line differentiation. "Mechanistically, the MLL1 fusion protein in acute myeloid leukemia (AML) causes abnormal recruitment of histone modification enzymes, including DOT1L (KMT4) and protein arginine methyltransferase (PRMT) 1, at target genes for epigenetic reprogramming, conferring stem cell-like properties." (PMID 37394580, 2023). "Notably, small-molecule inhibitors of DOT1L are currently undergoing clinical trials to treat acute myeloid leukemia (AML), suggesting the potential to develop novel drug therapies targeting against this family of proteins in brain tumors." (PMID 32375856, 2020). "CARM1 was reported to have pairwise synergistic interaction with other histone methyltransferases, like disruptor of telomeric silencing 1-like (DOT1L), jointly coordinating K562 (acute myeloid leukemia [AML]) cell survival." (PMID 40123976, 2025). "CRISPR/Cas9 screening platform have been used to identify genetic vulnerabilities in acute myeloid leukemia (AML) cells, including several established (such as DOT1L, BCL2, and MEN1) and novel (such as KAT2A) therapeutic targets for AML." (PMID 39696697, 2024). "Previous studies have uncovered an important role for DOT1L in driving pathogenesis of acute myeloid leukemias (AML) with mixed lineage leukemia (MLL) gene translocations." (PMID 32814769, 2020). "They identified numerous targets, including Bromodomain-containing Protein 4 (BRD4), Histone Methyltransferase DOT1L (DOT1L), and Multiple endocrine neoplasia type 1 (MEN1) for Acute Myeloid Leukemia (AML)." (PMID 38725484, 2024).
melanoma (11 papers, 2018 to 2024). A malignant, usually aggressive tumor composed of atypical, neoplastic melanocytes. "The human DOT1L gene is frequently mutated or deleted in melanoma and many of the detected missense mutations display the UV signature, i.e. consist of C to T transitions at di-pyrimidine sites as well as tandem CC to TT transitions." (PMID 31930303, 2020). "Then we examined BRaf and NRas status in DOT1L-null mouse melanomas and found that BRaf (V637, homolog to human BRaf V600) mutations are frequently observed in melanomas from Dot1l-null transgenic mice (n = 4/7)." (PMID 29343685, 2018). "Using enzyme-linked immunosorbent assays, we found that CPDs and 6–4 PPs photoproducts were significantly less efficiently repaired in melanoma cells with DOT1L mutations than that in those with WT DOT1L." (PMID 29343685, 2018). "Here tumor genome sequencing efforts have identified inactivating mutations in DOT1L in 4.4–15% of melanomas." (PMID 29343685, 2018). "Specifically, the DOT1L gene is located in a frequently deleted region and undergoes somatic mutation in human melanoma." (PMID 29343685, 2018). "Interestingly, inhibiting DOT1L, associated with the onset of melanoma, before the B-Raf inhibition showed more drug resistance than simultaneous inhibition of DOT1 and B-Raf using pinometostat and vemurafenib, respectively." (PMID 34691155, 2021). "Our data indicate that DOT1L loss of function alone is insufficient to induce melanoma development." (PMID 29343685, 2018). "Notably, levels of H3K79 methylation markedly decreased in cells with DOT1L mutations in comparison to cells with WT DOT1L (C021), with the DOT1L mutations detected in all the detected melanoma cell lines indicated." (PMID 29343685, 2018). "DOT1L is frequently mutated in human melanoma, leading to a reduced level of H3K79 methylation." (PMID 30466474, 2018). "In line with a role of this histone methylation in the GGR function, conditional-null mice with a DOT1L deletion in melanocytes provide a very efficient cancer model with melanoma being induced in nearly 50% of animals by 10 weeks after UV irradiation." (PMID 31930303, 2020). "In fact, the gene-encoding DOT1L, a histone methyltransferase required for H3K79 methylation, is frequently mutated in human melanoma." (PMID 32831131, 2020). "DOT1L therefore plays an essential role in UVR-stressed melanocytes to protect against the transition to melanoma." (PMID 29343685, 2018). "We then examined the effects of DOT1L mutations on H3K79 di-methylation on four cell lines, D11, D28, D22, and C025, derived from human melanomas with missense mutations." (PMID 29343685, 2018). "To better define the role of DOT1L in melanocytes and UVR-induced melanoma development in vivo, we specifically depleted DOT1L expression in melanocytes using conditional Dot1l knockout mice (Dot1lflox/flox), in which exon 2 of Dot1l was floxed." (PMID 29343685, 2018). "Our study identified 1518 genes whose gene body regions contain sites with decreased H3K79me2 levels in the DOT1L-mutant melanoma cell line C025 and shDOT1L-treated cell line C021." (PMID 29343685, 2018). "To characterize the molecular characteristics of Dot1l-null melanoma, we measured the mRNA expression of neural crest development genes, tumor-suppressor genes, and oncogenes in melanoma development by quantitative reverse-transcriptase PCR (qRT-PCR)." (PMID 29343685, 2018). "To identify any potential cooperation between the common oncogenic alterations with DOT1L mutation in melanoma development, we first analyzed the relationship between BRaf/NRas status and DOT1L status in the TCGA melanoma cohort." (PMID 29343685, 2018). "Here our data indicate that, in melanocytes and melanoma, DOT1L and H3K79 methylation is required for XPC recruitment and efficient NER, and loss of DOT1L leads to UV sensitivity and inefficient removal of UV photoproducts." (PMID 29343685, 2018).
melanoma (continued). "To identify how DOT1L protects against UVR in melanocytes, we examined UV response of melanoma cells with WT or different DOT1L mutants and found that melanoma cells with mutant DOT1L are more sensitive to UV irradiation than cells with WT DOT1L." (PMID 29343685, 2018). "CRISPR/Cas9 engineered DOT1L knockdown in HPMs and mouse B16 melanoma cells, which were pooled as heterogeneous transfected cells after drug selection, also failed to affect cell viability unless cells were UVB irradiated." (PMID 29343685, 2018). "Together with the identification of DOT1L mutations in human melanomas, these data suggest a UVR protective role for DOT1L in melanocytes." (PMID 29343685, 2018). "We treated melanoma cells with different doses of the DOT1L inhibitor EPZ-5676 and assessed its effects on H3K79 methylation and cell growth." (PMID 29343685, 2018). "Interestingly, mice genetically deleted for DOT1L develop melanomas upon UV irradiation, consistent with the frequent deletion of DOT1L observed in human melanomas." (PMID 34731255, 2021). "Our data suggest that DOT1L deletion alone is insufficient to induce melanoma." (PMID 29343685, 2018). "Furthermore, melanomas in UVB-irradiated Dot1l-null mice closely mimic the vertical phase of human melanoma histologically." (PMID 29343685, 2018). "In addition, our work on melanocytes with conditional knockout of Dot1l provides an UVR-dependent mouse model of melanoma." (PMID 29343685, 2018). "In contrast, DOT1L targets the DDB1 gene locus only in melanoma cell lines." (PMID 29343685, 2018). "Next, we focused on the role of DOT1L in the UVR response in melanocytes, as almost all DOT1L mutations are UV signature mutations, and UV irradiation is required in Dot1l-null-driven melanoma development." (PMID 29343685, 2018). "DOT1L depletion will cause UV-induced DNA damage not to be efficiently repaired, thus encouraging progression of melanoma." (PMID 30466474, 2018). "Next, we sought to understand the biological significance of DOT1L in melanomas." (PMID 29343685, 2018). "Moreover, a missense R409H germline DOT1L mutation has been identified in two members of a family with four melanoma cases, although this mutation does not impair significantly the H3K79 methyltransferase activity of the enzyme." (PMID 35495127, 2022). "Consistent with the protective role of DOT1L in UVR response, treatment of melanoma cells with the DOT1L inhibitor EPZ-5676 decreased cell viability following UVR." (PMID 29343685, 2018). "Aberrant DOT1L expression or enzyme activity has been found also in other non-hematologic cancers, including lung, melanoma, neuroblastoma, liver, and head and neck squamous cell carcinomas (HNSCCs)." (PMID 35495127, 2022). "Specifically, melanoma was observed in UVB-irradiated Dot1l-null mice, but not in unirradiated Dot1l-null mice." (PMID 29343685, 2018). "Importantly, in the absence of DOT1L, UVR-induced DNA damage is inefficiently repaired, so that DOT1L loss promotes melanoma development in mice after exposure to UVR." (PMID 29343685, 2018). "Unlike leukemia, DOT1L plays a repressive role in UV-induced melanoma development." (PMID 30466474, 2018). "Importantly, in the absence of DOT1L, UVR-induced DNA damage is inefficiently repaired such that DOT1L loss promotes melanoma development in mice after exposure to UVR." (PMID 29343685, 2018). "Interestingly, inhibition of DOT1L prior to the addition of a BRAF inhibitor, but not co-administration of both drugs, enhanced resistance of melanoma cells to the latter drugs." (PMID 35495127, 2022).
lung carcinoma (10 papers, 2016 to 2024). "The R231Q mutation variant of DOT1L selectively activates the MAPK/ERK signaling pathway in lung cancer cells by enriching H3K79me2 on the RAF1 promoter and epigenetically regulating the expression of downstream targets." (PMID 38525426, 2024). "The R231Q mutation of DOT1L induces resistance of lung cancer cells to cisplatin and vinorelbine both in vitro and in vivo." (PMID 38525426, 2024). "Of note, H3K79 methylation was found upregulated in lung cancer suggesting its association with lung tumorigenesis, but average DOT1L mRNA level in lung tumor tissues results comparable to that of paired normal lung tissues." (PMID 35495127, 2022). "For example, the mutation rate of DOT1L in lung cancer is about 3%." (PMID 38525426, 2024). "Contrary to previous observations in lung cancer cells, γH2AX requires DOT1L-mediated H3K79me and its absence leads to decreased γH2AX levels and reduced DNA damage repair in models of induced DNA damage." (PMID 38962004, 2024). "The variant with the strongest effect on H3K79me2, R231Q, enhances the substrate binding ability of DOT1L and promotes cell growth and drug resistance of lung cancer cells in vitro and in vivo." (PMID 38914477, 2024). "H3K79 methylation was up-regulated in lung cancer cell lines, but the role of DOT1L in lung cancer is unclear." (PMID 36420141, 2022). "DOT1L knockdown reduced H3K79 methylation and led to disturbed cell proliferation; additionally, chromosomal missegregation occurred in DOT1L-deficient lung cancer cells, resulting in cell cycle arrest at G1 phase and subsequent senescence." (PMID 30002791, 2018). "These seemingly contradictory results indicate a complex mechanism for H3K79 methylation in lung cancer, more studies are required to establish a link between different roles of DOT1L and H3K79 methylation." (PMID 30002791, 2018). "In lung cancer, over expression of DOT1L leads to RNAi mediated changes which takes part in tumoral genesis." (PMID 27713173, 2016). "In the absence of DOT1L mediated H3K79me, lung cancer cells are unable to repair DNA damage caused by division leading to accumulation of phosphorylation of ser 139 on histone H2AX (γH2AX) resulting in cell cycle arrest; a feature of cellular senescence." (PMID 38962004, 2024). "Interestingly, during the process of TGF-β1-induced epithelial-to-mesenchymal transition (EMT) in lung cancer, H3K79me3 was decreased without association with DOT1L expression; and DOT1L inhibitors, EPZ5676 and SGC0946, were not effective on EMT-related genes." (PMID 30002791, 2018). "DOT1L and H3K79me3 were identified as promising targets for the treatment of acute myelocytic leukemia (AML), but played a rather unclear role in lung cancer." (PMID 30002791, 2018). "In this screen, DOT1L deletion significantly impaired EMT, while increasing at the same time cell motility, a result suggesting a complex effect of DOT1L on epithelial/mesenchymal identity and migratory potential in lung cancer." (PMID 35495127, 2022). "In another study, DOT1L downregulation was shown to induce a nonproliferating multinucleated phenotype, with abnormalities in mitotic spindle formation and centrosome number in lung cancer cells, suggesting chromosome mis-segregation." (PMID 35495127, 2022).
prostate carcinoma (10 papers, 2016 to 2025). A carcinoma that arises from epithelial cells of the prostate gland. "A previous study showed that Dot1l was overexpressed in prostate cancer and associated with poor outcome." (PMID 33628364, 2021). "Chemical or genetic inhibition of Dot1l impaired the viability of androgen receptor-positive prostate cancer cells." (PMID 33628364, 2021). "In prostate cancer, DOT1L overexpression correlates with disease progression and it was suggested that it can be used as a biomarker for early detection." (PMID 34253709, 2021). "Thus DOT1L selectively regulates the tumorigenicity of AR-positive prostate cancer cells and is a promising therapeutic target for PCa." (PMID 32814769, 2020). "In prostate cancer, Dot1l directly methylates androgen receptor to regulate its activity." (PMID 27713173, 2016). "The histone methyltransferase DOT1L methylates lysine 79 (K79) on histone H3 and is involved in Mixed Lineage Leukemia (MLL) fusion leukemogenesis; however, its role in prostate cancer (PCa) is undefined." (PMID 32814769, 2020). "Of interest, DOT1L was recently shown to methylate non-histone proteins like the androgen receptor through recruitment of the PRNCR1 long non-coding RNA for subsequent activation of this receptor in prostate cancer after looping between enhancer and promoter sequences." (PMID 28804523, 2017).
viral infection (10 papers, 2015 to 2025). "We next sought to assess the effect of DOT1L knockout on the protein levels of key proteins that are associated with the activation of innate antiviral signaling during viral infection." (PMID 33363525, 2020). "Accordingly, Dot1L inhibition decreases the IFN-β promoter stimulation and RIG-I- mitochondria-associated viral sensor (RIG-I-MAVS) association upon viral infection." (PMID 32188146, 2020). "TRIM25 overexpression reverses the defective innate response mediated by Dot1L inhibition elicited upon virus infection or by overexpression of RIG-I signaling intermediates." (PMID 32188146, 2020). "Since H3K79 methylation does not affect influenza virus replication in cells with impaired IFN signaling, we analyzed the effect of Dot1L inhibitor in subsequent stages of viral infection." (PMID 29352168, 2018). "A DOT1L knocked-down stable cell line was created using lenti-viral infection, and overexpression of RE-IIBP successfully up-regulated the levels of H3K79me2." (PMID 26206755, 2015). "However, whether DOT1L plays a role in antigen-specific CD8+ T cells during viral infection remains unclear and requires further investigation." (PMID 38962004, 2024). "A previous study suggested that DOT1L silencing or inhibitor treatment suppresses IFN-β production triggered by TLR ligands and virus infection." (PMID 33363525, 2020). "In agreement with the role of H3K79 methylation in viral infection, alterations in RUBCN, TRIM25 and BCL3 gene expression in DOT1L down-regulated cells were found." (PMID 31727944, 2019). "In some cases, DOT1L inhibition also restored virally-suppressed interferon (IFN) and interferon stimulated gene (ISG) functions or alleviated pathology, indicating the role of this gene in facilitating viral replication, immune augmentation and promoting pathology following viral infection." (PMID 39392810, 2024).